ALB (albumin)
Diseases named in the same sentence as ALB in open-access papers (continued):
Sharing a sentence is not in itself a finding about the gene and the disease.
diabetes (continued). "In our data, the CFS was significantly associated with the markers of nutrition (BMI and serum albumin), the marker of inflammation (CRP) and comorbidity of diabetes and cardiovascular diseases, which were the etiologic factors of PEW." (PMID 37696942, 2023). "Red cell distribution width/albumin ratio (RAR) is thought to be associated with the prognosis of a variety of diseases, including diabetes and heart failure." (PMID 36814226, 2023). "Preoperative serum albumin levels (OR = 0.116, 95% CI 0.021-0.641, p=0.014) and diabetes mellitus (OR = 5.757, 95% CI 1.018-32.565, p=0.048) remained as independent predictors of 1-year mortality in the multivariate analysis." (PMID 37082727, 2023). "SFACS, BKACS, C-reactive protein, serum albumin, age, diabetes, presence of ischemic heart disease, and critical limb-threatening ischemia were significantly associated with 3-year and 10-year clinical outcomes in the univariate analysis." (PMID 36835836, 2023). "The integration of these innovative aspects represents a leap forward for biosensor, offering a more accurate, reliable, and efficient means of monitoring glycated albumin levels, a critical factor in diabetes management." (PMID 38125431, 2023). "A retrospective study performed by Davenport identified low post-sessional intracellular water, low serum albumin, diabetes mellitus, and higher co-morbidity as indicators for low convective volumes." (PMID 36829639, 2023). "An effect of diabetes on albumin excretion was also demonstratable in the present study; this effect was evident only in the low Cd burden group." (PMID 37755765, 2023). "In summary, our results confirm the view that in diabetes mellitus, systemic redox balance determined by albumin redox state is shifted towards oxidation." (PMID 38003446, 2023). "Independent hazard factors related to AL were further revealed via multivariate analysis, including albumin concentration, diabetes, mode of surgery, and type of resection." (PMID 37007118, 2023). "Age, sex, smoking status, coronary artery disease, diabetes mellitus, COPD, histology, surgical procedure, operative time, blood loss, albumin, FVC, FEV1, and DLCO correlated significantly with PPCs (p<0.05)." (PMID 37901337, 2023). "Independent factors (P < 0.05) associated with mortality in the multivariable Cox model in early dialysis start were: hypertension (HR 9.32, CI: 1.34–17.87), diabetes (HR 1.8, CI: 0.4–13.2) and albumin < 3.5 g/dL (HR 1.5, CI: 0.8–6.2)." (PMID 37286965, 2023). "In the final joint model, variables noted to significantly increase CVM risk included 10-year age increase, history of diabetes or CVD, 5 g/L serum albumin decrease, and doubling CRP levels." (PMID 37289366, 2023). "Hypoalbuminemia has been associated with an increased incidence of various cardiovascular diseases such as ischemic heart disease, diabetes, and stroke, and a linear increase in the incidence of AF with decreasing serum albumin levels has been reported." (PMID 37834958, 2023). "The last available serum creatinine and urine albumin/creatinine ratio (UACR) in patients with T1DM or T2DM diabetes recorded on the DIAMOND database were used for analysis." (PMID 36620790, 2023). "The objectives of the study were to assess the utility of CEA, CRP, serum albumin level, hemoglobin, and LDH as biomarkers of cancer risk and the biological implications of diabetes on the evolution and prognosis of oncological patients." (PMID 37627906, 2023). "The CCI was a better predictor than models containing age, diabetes, cardiovascular disease, and albumin and a strong predictor of mortality in incident PD patients." (PMID 38076234, 2023). "The 12 most important features were hemoglobin, HbA1c, neutrophil percentage, serum albumin, duration of diabetes, plasma fibrinogen, HDL-C, SBP, DBP, DF, Lp(a), and BMI." (PMID 37308973, 2023).
diabetes (continued). "Age, education, Poverty-Income Ratio (PIR), Body Mass Index (BMI), smoking, alcohol consumption, presence of diabetes, albumin levels, heart failure, and zinc intake all exhibited significant differences between the two groups." (PMID 37810930, 2023). "eGFR < 60 ml/min/1,73m2 oder Albumin/Kreatinin-Ratio ≥ 30 mg/g oder beides) nach Korrektur für demografische Faktoren durch Diabetes mellitus verursacht werden." (PMID 37101040, 2023). "Body weight, body mass index, prevalence of diabetes, hemoglobin, hematocrit, serum albumin, eGFR, ICW, and fat mass were significantly higher in the fluid retention (−) group than in the fluid retention (+) group." (PMID 38155663, 2023). "Laut Empfehlungen sollten die geschätzte glomeruläre Filtrationsrate (eGFR) und das Albumin-Kreatinin-Verhältnis im Urin mindestens 1‐mal pro Jahr bei allen Menschen mit Diabetes mellitus Typ 2 bestimmt werden." (PMID 37955643, 2023). "In the present study, we show, in good agreement with several other studies, that the albumin redox state of people with diabetes correlates with age, diabetes duration, and the quality of disease control." (PMID 38003446, 2023). "BMI, hemoglobin, the serum albumin level, and the glycated hemoglobin value (for patients with diabetes) decreased while the UPCR level increased with progression though the stages of CKD." (PMID 37002509, 2023). "It is possible that we have underestimated the amount of albumin in urine samples from subjects with diabetes and high Cd burden." (PMID 37755765, 2023). "Because many immunoglobulins are lost from urine, low plasma albumin affects antibody formation, and abnormal metabolism in patients with diabetes increases the possibility of infection in proteinuria patients." (PMID 37599328, 2023). "Patients with diabetes should be routinely screened for DKDwith assessments of both urinary albumin and kidney function." (PMID 36726361, 2023). "Further, the putative gene network generated from these enriched pathways revealed experimentally induced diabetes, renal tubular injury, and decreased levels of albumin as part of mapping under ‘disease and function’." (PMID 36934129, 2023). "The analysis indicated that eGFR (cystatin C), diabetes mellitus, liver disease, plasma albumin level on admission, and plasma BNP level at discharge were associated with 3-year all-cause mortality." (PMID 37187794, 2023). "In the LASSO logistic regression analysis, 28 features were reduced to 11 candidate predictors with nonzero coefficients, including numbers of tumors, integrality of the tumor capsule, HAVF, diabetes, cirrhosis, ALB, GLB, DBIL, AST and PVTT." (PMID 37847433, 2023). "In patients with diabetes, the risk factors of HCC were high fibrosis‐4 (FIB‐4) index, male sex, hypertension, low hemoglobin A1c and albumin levels, and high body mass index (BMI), and gamma‐glutamyl transpeptidase levels." (PMID 37644826, 2023). "A meta-regression analysis of 32 randomized trials showed that a 10% reduction in urinary albumin excretion assessed by UACR and 24-hour urine collection was associated with a 13% decrease in MI incidence in patients with diabetes or hypertension." (PMID 37817566, 2023). "There were significant differences among different HbA1c levels in age, diabetes duration, TC, TG, mean sensor glucose, albumin, serum creatinine, eGFR and history of atherosclerotic cardiovascular disease." (PMID 37891255, 2023). "This retrospective cohort study focused on patients with type 2 diabetes mellitus who had a baseline estimated glomerular filtration rate (eGFR) of > 30 mL/min/1.73 m2, and a urinary albumin-to-creatinine ratio < 30 mg/gCr." (PMID 37773087, 2023). "Megalin gene knock-out was associated with decreased urinary reabsorption of albumin and RBP in mice with streptozotocin-induced diabetes and Akita mice." (PMID 36836700, 2023).
diabetes (continued). "Diabetes induced significant alterations in renal glomerular structure, increased albumin and PCX levels in urine, and highly decreased PCX protein and mRNA expression of renal tissue." (PMID 37685845, 2023). "Cardiovascular major adverse cardiovascular events occurred in 422 (19.3%) patients; predictors included prior history of diabetes (1.39 [1.13–1.71]; P = 0.002) and serum albumin reduction of 5 g/L (1.20 [1.05–1.36]; P = 0.006)." (PMID 37289366, 2023). "Multivariate analysis indicated that low albumin concentration (P = 0.001), presence of diabetes (P = 0.025), laparoscopic method (P < 0.001), total gastrectomy (P = 0.003), and proximal gastrectomy (P = 0.002) were predicting factors for AL." (PMID 37007118, 2023). "Blood glucose, HbA1c, and glycated albumin are commonly used indicators for diagnosing diabetes or monitoring blood glucose control." (PMID 37775738, 2023). "The covariates included age, gender, race, educational level, marital status, total energy intake, physical activity, smoking, hypertension, diabetes, urine creatinine, albumin and marihuana use." (PMID 37404817, 2023). "The MFP model was selected to be the final model, including gender, the use of insulin, duration of diabetes, urinary albumin-to-creatinine ratio, and serum phosphorus." (PMID 37008912, 2023). "For example, some studies have reported that diabetes, serum albumin, and other factors have predictive value for PDAP prognosis, while other studies believe that these factors cannot be used as outcome predictors for PDAP." (PMID 37550622, 2023). "Preoperative serum albumin level was an independent predictor of 1-year mortality along with diabetes mellitus." (PMID 37082727, 2023). "Preoperative serum albumin levels (OR = 0.116, 95% CI 0.021-0.641, p=0.014) and diabetes mellitus (OR = 5.757, 95% CI 1.018-32.565, p=0.048) remained independent predictors of mortality." (PMID 37082727, 2023). "Among all clinical factors, hypertension, diabetes, serum albumin, and serum Hb significantly differed among the CKD groups; therefore, they were included as confounders in the multivariate analyses." (PMID 36624472, 2023). "Herein, we investigated some essential metabolic biomarkers for diabetes mellitus, namely glucose, adiponectin, and albumin." (PMID 37760819, 2023). "In contrast, studies reveal significant correlation between malnutrition and serum albumin (depletion) among elderly patients with diabetes." (PMID 36694739, 2023). "The hazard ratios have been adjusted to DEHP, IS, age, sex, diabetes, hypertension, cardiovascular disease, dialysis vintage, dialysis adequacy (Kt/V), and serum albumin." (PMID 37936044, 2023). "Diabetes mellitus, one of the primary diseases, was seen significantly more frequently in patients with hypoalbuminemia in all baseline, first-year mean, and mean albumin value groups." (PMID 36762995, 2023). "Logistic regression analysis showed that age, diabetes mellitus, preoperative hemoglobin, and preoperative serum albumin level showed a difference with p<0.05 for predicting 1-year mortality of patients." (PMID 37082727, 2023). "In patients with diabetes, PTH level, ferritin ≥ 800 and serum albumin were significantly associated with higher mortality." (PMID 36719878, 2023). "Renal injury in patients with diabetes is reflected by increased urinary albumin excretion and decreased GFR." (PMID 37109492, 2023). "Blood glucose, glycated albumin (GA), and glycated hemoglobin are the three main indicators used to regulate blood glucose levels in individuals with diabetes." (PMID 38125431, 2023). "The potential confounding factors in the multivariate analysis were as follows: age, sex, duration of diabetes, cardiovascular disease, diminished renal function, anemia, and serum albumin, and the adjustment was made accordingly." (PMID 37510519, 2023).
diabetes (continued). "Albumin-creatinine ratios – or some other validated measurement of albumin excretion – should be monitored at least annually after a diabetes duration of five years has been reached in individuals with type 1 diabetes." (PMID 38192517, 2023). "The significant independent predictors of the CIMT were diabetes duration, BMI, albumin/creatinine ratio, and serum cholesterol." (PMID 37692464, 2023). "A biosensor specifically engineered to detect glycated albumin (GA), a critical biomarker for diabetes monitoring, is presented." (PMID 38125431, 2023). "Elevated levels of PCT, CRP, NEUT and decreased levels of PLT and ALB were observed from patients with diabetes in the severe group, where level of N increased both quantitatively and as a categorical variable." (PMID 37790212, 2023). "We thus aimed to investigate possible differences of albumin redox fractions HMA, HNA1, and HNA2 between people with T1DM and T2DM and the association with patient age, diabetes duration, and glycaemic control." (PMID 38003446, 2023). "Cox proportional hazard model revealed that the hANP level remained independently associated with hospitalization due to AHF after adjusting for sex, age, hemoglobin, albumin, and history of diabetes." (PMID 36941501, 2023). "Fractional serum fructosamine (FSF) and glycated albumin (GA) represent the glycated proteins that offer alternative markers for evaluating glycemic control in patients with diabetes." (PMID 38136081, 2023). "The primary outcomes were DKD and DR events, and secondary outcomes were estimated glomerular filtration rate (eGFR), urinary albumin-to-creatinine ratio (ACR) in diabetes, and proliferative diabetic retinopathy (PDR)." (PMID 36926020, 2023). "One study indicated that GSH significantly suppressed the diabetes-induced increase in urinary 8-hydroxy-2′-deoxyguanosine, albumin, and creatinine levels." (PMID 36644578, 2023). "Sulodexide was shown to be effective in restoring the glycocalyx thickness and showed a trend towards normalization of systemic albumin clearance in a study of type 2 diabetes mellitus patients." (PMID 37180718, 2023). "Among the three α-Klotho tertiles, differences with statistical significance were observed in age, gender, race, education level, BMI, HDL-C, triglycerides, ALT, AST, diabetes, hypertension, PP, and urine albumin (all p < 0.05)." (PMID 36675565, 2023). "Patients with diabetes should be routinely screened for DKD withassessments of urinary albumin and kidney function, following currentDiabetes Canada guidelines." (PMID 36726361, 2023). "For CKD patients with diabetes, the multivariate linear regression analysis revealed that hands ESC showed significant associations with age, BMI, hemoglobin, and serum albumin (β in model 2: −0.21, 0.47, 1.32, and 10.77, respectively)." (PMID 38202194, 2023). "Xu Jiang’ study indicates that the excretion of β2-MG increases in the early course of DKD, whereas urinary albumin excretion is normal in patients with diabetes." (PMID 37929213, 2023). "Other characteristics, including age, sex, albumin level, C-reactive protein level, steroids, diabetes mellitus, purpose of TIVAP implantation, primary site of cancer, catheter length, and location of catheter tip, did not demonstrate significant differences." (PMID 37902854, 2023). "The risk factors included the following: angiotensin-converting enzyme inhibitor/angiotensin receptor blockers, open thoracotomy, pneumonectomy/esophagectomy, diabetes mellitus, cerebrovascular disease, and low albumin level." (PMID 37430359, 2023). "Those patients developing AKI were more likely to have advanced age, diabetes, hypertension, lower albumin concentration, lower Hematocrit (%), preoperative malperfusion syndromes, and preoperative renal malperfusion." (PMID 36836115, 2023).
diabetes (continued). "In the multivariable linear regression analysis adjusted with age, sex, baseline eGFR, hypertension, diabetes mellitus, and serum albumin level, 913 CpGs still continued to have a significant relationship with eGFR changes." (PMID 37510393, 2023). "FT3 was also positively related to eGFR, lymphocyte, TC, LDL-C, and HDL-C, and was negatively related to age, onset age, diabetes duration, HbA1c, creatinine, 24-h urine albumin, and hsCRP (All P < 0.05)." (PMID 37700304, 2023). "The lowest Akaike information criterion was obtained with a model including interaction terms of sex, overweight, age (in overweight subjects), albumin, hypertension, diabetes and renal disease with time." (PMID 37198577, 2023). "In our study, daily administration of 2000 mg ginger significantly elevated serum albumin (by 8%) in patients with diabetes and ESRD." (PMID 37228303, 2023). "The last step revealed that the significant (independent) predictors of CIMT were only diabetes duration, BMI, albumin/creatinine ratio, and cholesterol." (PMID 37692464, 2023). "Nonetheless, in individuals with diabetes, the serum albumin level is inversely proportional to the diabetic condition, as it tends to decrease in diabetes mellitus." (PMID 37693342, 2023). "The features included in the PKU-CKD model were age, gender, estimated glomerular filtration rate (eGFR), urinary albumin–creatinine ratio (UACR), albumin, hemoglobin, medical history of type 2 diabetes mellitus (T2DM), and hypertension." (PMID 36836039, 2023). "The two measures of kidney function used to define and stage CKD, the eGFR and urinary albumin/creatinine ratio (UACR), are consistently associated with cardiovascular events and mortality in diabetes." (PMID 36347992, 2023). "The rats developed kidney disease (Diabetic nephropathy, DN) as indicated by the rise in urine albumin-to-creatinine (ACR) ratio from 6th weeks onwards after diabetes induction, relative their own baseline (before diabetic induction)." (PMID 37251672, 2023). "In type 2 diabetes mellitus (T2DM) patients, the reduced serum albumin level is a risk factor for T2DM development and progression, although this conclusion is controversial." (PMID 36747238, 2023). "Occurrence of new onset HF was significantly related to low serum albumin concentration after adjusting for age, ejection fraction, renal function, inflammation, BP, diabetes and clinical presentation in 7192 patients with acute coronary syndrome." (PMID 37980510, 2023). "Age, sex, diabetes mellitus, serum albumin, systolic blood pressure, smoking history, uric acid and time stratified eGFR, log(urine protein creatinine ratio), total cholesterol, C- reactive protein." (PMID 36715437, 2023). "The factors related to low HRV included advanced CKD, diabetes mellitus, low serum albumin, and proteinuria." (PMID 36832273, 2023). "An audit tool was used to collect patients’ information including gender, age, type of diabetes, serum creatinine, urinary albumin excretion, albumin creatinine ratio (ACR), body mass index, and last available glycated hemoglobin (HbA1c)." (PMID 36620790, 2023). "Uncontrolled diabetes, anemia, low albumin, etc. undoubtedly have an adverse effect on wound healing, but it is impossible to correct them pre-operatively as patients with secondary peritonitis require EAS." (PMID 38024020, 2023). "The AUC of GNRI was also statistically significant and was superior to albumin in all, men, women, BMI ≥ 22, and diabetes duration ≥ 5 years subgroups." (PMID 36819693, 2023). "This chronic complication of diabetes was primarily characterized by an increased urinary albumin excretion or decreased estimated glomerular filtration rate (eGFR), or both." (PMID 37298010, 2023). "We aimed to evaluate the redox state of albumin in patients with DM to investigate possible correlations with age, diabetes duration, and disease control status." (PMID 38003446, 2023).